IGFBP7 (insulin like growth factor binding protein 7)
Diseases named in the same sentence as IGFBP7 in open-access papers (continued):
Sharing a sentence is not in itself a finding about the gene and the disease.
gastric cancer (34 papers, 2008 to 2025). A primary or metastatic malignant neoplasm involving the stomach. "Lastly, although IGFBP-7 overexpression is associated with worsened patient survival in glioma, bladder, and stomach cancer, it induces both pro- and anti-inflammatory immune cell infiltration." (PMID 41226289, 2025). "Downregulation of IGFBP7 has been reported to be involved in oncogene-induced senescence in PTC, whereas in gastric cancer, IGFBP7 expression has been linked to cancer progression." (PMID 40430098, 2025). "A previous study showed that increased IGFBP7 expression is associated with poor prognosis and immune infiltration in gastric cancer." (PMID 40224214, 2025). "For example, Li and colleagues reported that high insulin-like growth factor binding protein 7 (IGFBP7) expression was associated with a poor prognosis in gastric cancer patients with the infiltration of TAMs." (PMID 39889181, 2025). "IGFBP7 is closely associated with bladder cancer, gastric cancer, breast cancer, lung cancer and acute myeloid leukemia." (PMID 37088808, 2023). "Herein, we tried to explore the diagnostic value of insulin-like growth factor binding protein 7 (IGFBP7) in gastric cancers." (PMID 37304887, 2023). "TCGA showed that IGFBP7 mRNA was dysregulated and associated with prognosis in gastric cancer patients." (PMID 37304887, 2023). "Low tumor IGFBP-7 levels have been associated with poor prognosis in gastric cancer and breast cancer." (PMID 33767994, 2021). "COL12A1 was upregulated in gastric cancer and positively associated with tumor invasion and clinical stage and was also significantly correlated with IGFBP7 (|r| = 0.426016684, p = 5.75765E-18)." (PMID 34745945, 2021). "A recent study showed that an elevated IGFBP7 expression level in gastric cancer is associated with invasion, tumor progression and recurrence as well as poor survival." (PMID 27600085, 2016). "Notably, elevated levels of LGALS1 and IGFBP7 were linked to an adverse survival prognosis in individuals with gastric cancer from Kaplan‐Meier Plotter database." (PMID 40995693, 2025). "Treatment of macrophages and gastric cancer cells with recombinant IGFBP7 further showed that IGFBP7 promoted tissue-associated macrophages (TAM)/M2 polarization via FGF-2/Fibroblast Growth Factor Receptor 1 (FGFR-1)/Phosphoinositide 3-kinases (PI3K)/Protein kinase B (Akt) axis." (PMID 39045455, 2024). "In summary, our present study offers valuable information regarding the diagnostic efficacy of serum IGFBP7 in gastric cancer patients and advocates that IGFBP7 might be a potential serological marker for the detection of gastric cancer." (PMID 37304887, 2023). "Therefore, in the present study, we will focus on the early diagnostic value of serum IGFBP7 in gastric cancer." (PMID 37304887, 2023). "This study indicated that serum IGFBP7 might act as a potential early diagnostic marker for gastric cancers." (PMID 37304887, 2023). "Recently, a study revealed that the reduced expression of IGFBP7 in gastric cancer cells and tissues might be mainly caused by the aberrant high methylation of IGFBP7." (PMID 37304887, 2023). "Extended to the present study, we acknowledged that IGFBP7 might also have early diagnostic value in gastric cancers with an AUC of 0.773 (95% CI [0.701–0.845]) in the training cohort and 0.778 (95% CI [0.673–0.882]) in the independent validation cohort." (PMID 37304887, 2023). "In the context of gastric cancer (GC) research, recent investigations have revealed that insulin-like growth factor binding protein 7 (IGFBP7), secreted by cancer-associated fibroblasts (CAFs), plays a pivotal role in the progression of GC." (PMID 40485724, 2025). "Clinically, elevated expression of HOXA1, PITX2, MCOLN1, RAB3A, LGALS1, and IGFBP7 constitutes a prognostic signature correlating with poor outcomes of gastric cancer patients." (PMID 40995693, 2025).
gastric cancer (continued). "In summary, our findings reveal that PITX2 is significantly linked to unfavorable outcomes in gastric cancer and modulates the expression of lysosomal exocytic genes, including MCOLN1 and RAB3A, which enhance the secretion of LGALS1 and IGFBP7." (PMID 40995693, 2025). "BTG1 was reported to protect cells from oncogenic transformation; IGFBP7+ CAF was reported to promote gastric cancer; CAF-derived MFAP5 activated cell growth and migration in oral tongue squamous cell carcinoma via activation of MAPK and AKT pathways." (PMID 38686196, 2024). "Similar results were recently confirmed in gastric cancer, where IGFBP7 was mainly expressed by myofibroblastic CAFs." (PMID 39045455, 2024). "Then, increased secretion of insulin-like growth factor binding protein-7 (IGFBP7) from these CAFs augmented gastric cancer cells’ migration and invasion capabilities and induced stemness." (PMID 38562556, 2024). "TGF-β also promoted CAFs to secrete Insulin-like Growth Factor Binding Protein-7 (IGFBP7) that augments the stemness of gastric cancer cells." (PMID 38562556, 2024). "Transcriptome data of gastric cancer patients showed that high expression of IGFBP7 was correlated with a high infiltrating pattern and poorly differentiated phenotype, which exhibit poor prognosis." (PMID 38562556, 2024). "The specific mechanism by which IGFBP7 induces biological changes in gastric cancer is still subject to further research." (PMID 37568781, 2023). "Our work suggests that IGFBP7 is a novel predictive marker for clinical outcomes in gastric cancer patients." (PMID 37568781, 2023). "In the training cohort, serum IGFBP7 levels of male gastric cancer patients were lower than those of female patients (p < 0.0001)." (PMID 37304887, 2023). "Then, we examined the expression of serum IGFBP7 and found that serum IGFBP7 expressed lower in gastric cancer patients than normal controls both in training and independent validation cohorts (p < 0.0001)." (PMID 37304887, 2023). "From the TCGA database, we found that IGFBP7 mRNA was overexpressed in gastric cancer tissues in comparison to adjacent normal tissues." (PMID 37304887, 2023). "ELISA test showed that in the training cohort, the mean concentration ± standard deviation of serum IGFBP7 level in gastric cancer patients was 1.580 ± 0.198 ng/ml, which was lower than in the normal control group (1.850 ± 0.328 ng/ml, p < 0.0001)." (PMID 37304887, 2023). "In early-stage gastric cancer patients, the serum levels of IGFBP7 were also lower when compared with normal control groups in both cohorts (both p < 0.0001)." (PMID 37304887, 2023). "In our present study, serum IGFBP7 protein was also found to be downregulated in gastric cancer patients." (PMID 37304887, 2023). "Previous results suggested that IGFBP7 was correlated with the immune cell infiltration of gastric cancer." (PMID 36043552, 2023). "While, clinical cohort studies have implied an oncogenic role of IGFBP7 in oesophagus cancer and stomach cancer." (PMID 36681667, 2023). "We previously reported that IGFBP7 plays a role in maintaining mRNA stability of oncogenic lncRNA UBE2CP3 by RNA-RNA interaction in gastric cancer (GC)." (PMID 36681667, 2023). "In our study, we found that serum IGFBP7 protein was down-expressed in gastric cancer patients in comparison to normal volunteers." (PMID 37304887, 2023). "In this study, we first analyzed the expression levels and prognostic value of IGFBP7 mRNA in gastric cancers from The Cancer Genome Atlas (TCGA) database." (PMID 37304887, 2023). "In the independent validation cohort, the serum IGFBP7 level in gastric cancer group was 1.592 ± 0.253 ng/ml, lower than in the normal control group (2.011 ± 0.563 ng/ml, p < 0.0001)." (PMID 37304887, 2023). "From overall survival analysis, gastric cancer patients with high expression of IGFBP7, CCN2, CCN3, CCN1, CCN5 or CCN4 would have a poor survival time (all p < 0.05)." (PMID 37304887, 2023).
gastric cancer (continued). "That is, IGFBP3, IGFBP4, and IGFBP7 expression levels were higher in gastric cancer patients vs. normal in the Oncomine data." (PMID 34745945, 2021). "Although collagen and IGFBP7 were all closely related to cancer progression, few studies have focused on the contribution of IGFBP7 in gastric cancer." (PMID 34745945, 2021). "COL4A1 overexpression has previously been shown to be correlated with overall survival in gastric cancer; it was correlated with IGFBP7 with p = 6.99147E-33 in our study." (PMID 34745945, 2021). "Expression levels of IGFBP3, IGFBP4, and IGFBP7 were significantly elevated in gastric cancer tissues, whereas those of IGFBP1 were reduced in normal tissues." (PMID 34745945, 2021). "Our study focused on the prognostic value of IGFBP1–6 in gastric cancer; however, IGFBP7 is also significantly upregulated in STAD patients and closely related to prognosis." (PMID 34745945, 2021). "This was the first bioinformatic analysis study to describe the involvement of IGFBPs, especially IGFBP7, in gastric cancer development through the extracellular matrix." (PMID 34745945, 2021). "Some initial experiments have implied that IGFBP7 is upregulated in gastric cancer patients matched to paired normal tissue based on immunohistochemistry and, quantitatively, on real-time polymerase chain reaction (qRT-PCR)." (PMID 32500027, 2020). "Additionally, IGFBP7 regulates cell proliferation and migration in gastric cancer through the JAK-STAT signaling pathway." (PMID 40444282, 2025). "Mechanistically, HOXA1‐PITX2 complex facilitates the expression of mucolipin 1 (MCOLN1) and RAS‐related protein Rab‐3A (RAB3A), which drive lysosomal exocytosis of galectin‐1 (LGALS1) and insulin like growth factor binding protein 7 (IGFBP7) from senescent gastric cancer cells." (PMID 40995693, 2025). "In addition, the IGFBP7 methylation level was negatively related to IGFBP7 expression in gastric cancer." (PMID 37660019, 2023). "Result for measurement of IGFBP7 in the diagnosis of gastric cancer." (PMID 37304887, 2023). "Although our study applied independent validation (i.e., patients enrolled from different time period) to confirm the diagnostic value of serum IGFBP7 in gastric cancer, the sample size was small and bias should not be ignored." (PMID 37304887, 2023). "The potential relationship between serum IGFBP7 protein and IGFBP7 methylation might be used to speculate that the downregulation of serum IGFBP7 in gastric cancer might be influenced by the upregulation of IGFBP7 DNA methylation." (PMID 37304887, 2023). "This study first proposed that IGFBP7 might affect gastric cancer development by modulating the ECM." (PMID 34745945, 2021). "Among the identified DEGs, we found that 7 genes (IGFBP7, LOX, NRP1, PRSS3, DPP3, EFNA3, and CD73) were also differentially expressed in tumor tissues and associated with a poor or better prognosis in patients with gastric cancer." (PMID 34659527, 2021). "The topmost molecular network in the intestinal subtype on IPA network analysis showed increased expression of SULF1, HGF, SPARC, SERPINH1, and IGFBP7, which have been shown to contribute to the growth and survival of tumor cells, tumor invasion, metastasis, and poor survival in gastric cancer." (PMID 34885041, 2021). "These authors observed significant upregulation of IGFBP7 in undifferentiated cancers matched to the differentiated ones, indicating that IGFBP7 may participate as a critical functional component in gastric cancer differentiation." (PMID 32500027, 2020). "Also, IGFBP7 (insulin-like growth factor binding protein 7), has been reported as epigenetically down-regulated and an independent prognostic factor in gastric cancer, leading to increased cell growth, invasion and migration." (PMID 32511227, 2020). "As opposed to this, decreased IGFBP7 expression was also reported to be associated with tumor progression and poor survival in gastric cancer." (PMID 27600085, 2016).
gastric cancer (continued). "In addition to GBMs, high vascular expression of IGFBP7 has been shown in some peripheral tumours, including oesophagus, lung and stomach cancers." (PMID 20959824, 2010). "Likewise, IGFBP-7 has a biphasic response in gastric cancer proliferation and metastatic potential." (PMID 41226289, 2025). "Moreover, increased gastric cancer cell growth, invasion, and migration were identified following IGFBP7 knockdown, and gastric cancer cell growth inhibition and apoptosis were identified following IGFBP7 upregulation." (PMID 37660019, 2023). "Using the same cutoff value of 1.515 ng/ml, in the independent validation cohort, IGFBP7 could identify gastric cancers with an AUC value of 0.758 (95% CI [0.664–0.852]), a sensitivity of 34.5% (95% CI [22.6–48.7]), and a specificity of 85.5% (95% CI [72.8–93.1])." (PMID 37304887, 2023). "Furthermore, the IGFBP7 mRNA levels in Lauren type of gastric cancer were also explored." (PMID 33531979, 2021). "However, the role of IGFBP7 in gastric cancer (GC) is still undetermined." (PMID 33531979, 2021). "A constructive theory was identified originating from a correlation between the IGFBP7 expression and the depth of tumor invasion, the presence and the number of metastatic lymph nodes, distant metastasis/recurrence, or pathological stage in the stomach cancer individuals." (PMID 32500027, 2020). "Furthermore, the suppression of IGFBP7 expression has been demonstrated to impede GC cell proliferation and invasiveness in both in vitro and in vivo models, underscoring the potential of IGFBP7 as a therapeutic target in gastric cancer treatment." (PMID 40485724, 2025). "Fibroblast-secreted IGFBP-7 has also been shown to promote macrophage polarization through FGF2/AKT signaling mechanisms and reduce survival outcomes in gastric cancer." (PMID 41226289, 2025). "TGF-β signaling promoted the expression of IGFBP7 in CAFs, which in turn enhanced fibroblast growth factor-2 (FGF-2) expression in gastric cancer and resulted in increased macrophage infiltration and poor prognosis." (PMID 39045455, 2024). "Differential expression analysis showed that IGFBP7, CCN2, ESM1, CCN4 and CCN6 mRNA were over-expressed in gastric cancer tissues while CCN5 mRNA was down-expressed (all p < 0.05)." (PMID 37304887, 2023). "We found that IGFBP7 and CCN5 had significant abnormal expression between gastric cancers and adjacent normal tissues, and these two IGFBP-rPs were associated with both overall survival and disease-free survival of gastric cancer patients." (PMID 37304887, 2023). "Survival analysis also showed that GC patients with high expression of IGFBP7 possessed a relatively poor prognosis (OVS + DFS) in TCGA stomach cancer cohort and the GSE62254 stomach cancer cohort, suggested that IGFBP7 functioned as an oncogene in GC." (PMID 34274947, 2021). "The similar result has been published in non-small cell lung cancer patients, which further indicated that the downregulation of IGFBP7 protein was not specific in gastric cancer." (PMID 37304887, 2023). "By qRT-PCR to examine the IGFBP7 expression level, they identified IGFBP7 in 138 samples of gastric cancer and adjacent nontumour tissue." (PMID 37660019, 2023). "Moreover, the MSLN, SPP1, THBS2, SPARC, FN1, IGFBP7, VCAN were up-regulated in gastric carcinoma samples, while FGA was down-regulated." (PMID 36842141, 2023). "However, few studies have investigated the relationship between IGFBP7 and collagen-containing ECM formation in gastric cancer." (PMID 34745945, 2021). "The IGFBP7 gene was upregulated in diffuse-type gastric cancer and in 22 gastric cancer/nontumour mucosa paired tissues samples." (PMID 18827816, 2008). "Three of these are known to be involved in gastric cancer: MMP7, SPARC, and SOD2, and the other four have no such reported associations (INHBA, IGFBP7, NEK6, and LUM)." (PMID 18827816, 2008).
heart failure (32 papers, 2020 to 2026). Inability of the heart to pump blood at an adequate rate to meet tissue metabolic requirements. "Hs-TNT, GDF 15,10 and IGFBP-7 are associated with myocardial injury, the latter particularly in patients with heart failure." (PMID 40496590, 2025). "What is more, IGFBP7 concentration determined on hospital admission was shown to have no additional diagnostic value for confirming the exacerbation of heart failure symptoms." (PMID 38673493, 2024). "In a pressure overload mouse heart failure model, IGFBP7 deficiency attenuated cardiac dysfunction by reducing cardiac inflammatory injury, tissue fibrosis, and cellular senescence." (PMID 39045455, 2024). "In heart failure, IGFBP7 has been associated with abnormalities in diastolic filling and left atrial dilation." (PMID 38255264, 2024). "IGFBP7 has already been suggested as a biomarker of atherosclerosis and heart failure, and mutations in this gene are known to lead to vascular and valvular pathologies." (PMID 37036839, 2023). "Both heart failure associated IGFBP7 expression (p = 0.02) and cardiac hypertrophy associated PLC expression (p = 0.041) showed a similar decrease." (PMID 35360018, 2022). "Elevated IGFBP7 levels are associated not only with established risk factors of heart failure such as coronary atherosclerosis, kidney function and glucose metabolism disturbances, but also with a marker of myocardial damage or overload, TnT." (PMID 35204773, 2022). "In multiple linear regression analyses the strongest variables independently associated with higher concentrations of IGFBP7 were creatinine, age and heart failure (all p < 0.0001)." (PMID 34217226, 2021). "Similarly, elevated IGFBP7 levels are associated with adverse outcomes in heart failure, particularly in heart failure with preserved ejection fraction (HFpEF), aiding in diagnosis, prognosis, and prediction of hospitalization and mortality." (PMID 40823165, 2025). "Additionally, GDF-15, insulin-like growth factor-binding protein-7 (IGFBP-7), NT-proBNP, and hsTropT predict heart failure hospitalization, while GDF-15 and IL-6 are associated with major bleeding events." (PMID 40744929, 2025). "Data on the role of IGFBP7 as a diagnostic and prognostic marker in heart failure are divergent." (PMID 38673493, 2024). "For heart failure hospitalization, 4 biomarkers - GDF-15, IGFBP-7, NT-proBNP and hsTropT - were significantly associated with the outcome, with NT-proBNP and GDF-15 being among the most important risk predictors." (PMID 40744929, 2025). "IGFBP-7 demonstrates strong independent prognostic value as a reliable biomarker for heart failure patients across the spectrum of ejection fraction, including both HFrEF and HFpEF populations." (PMID 41214779, 2025). "Excitingly, endothelial-specific IGFBP-7 knockout and therapeutic targeting of IGFBP-7 using a vaccine-based approach both ameliorated cardiac dysfunction in a pressure overload model of heart failure." (PMID 41226289, 2025). "While the mechanism of action of IGFBP subtypes is a matter of ongoing research, previous work has shown that IGFBP‐7 promotes cardiomyocyte senescence and mediates inflammatory processes in patients with heart failure with preserved ejection fraction (HFpEF)." (PMID 39600082, 2024). "Still, it is intriguing that upregulation of IGFBP7 has been described in several conditions relevant to diabetes development such as: diabetic kidney disease, heart failure, and fat storage in the liver." (PMID 39280605, 2024). "Antibody-mediated IGFBP7 neutralization reversed IGFBP7-induced suppression of Forkhead box O3 (FOXO3a), thereby restoring DNA repair and reactive oxygen species detoxification signals and attenuated heart failure in mice." (PMID 39045455, 2024). "Elevated levels of insulin-like growth factor binding protein 7 (IGFBP7) have been observed in patients with heart failure and correlate with worse disease outcomes." (PMID 36936778, 2023).